CHD7 (chromodomain helicase DNA binding protein 7)
Diseases named in the same sentence as CHD7 in open-access papers (continued):
Sharing a sentence is not in itself a finding about the gene and the disease.
CHARGE syndrome (continued). "Furthermore, on the basis of the overlap in clinical features between zebrafish chd7 morphants and CHARGE syndrome, we suggest zebrafish can be a valuable in vivo tool to further understand the pathophysiological mechanisms underlying the abnormalities associated with CHARGE syndrome." (PMID 22363697, 2012). "Identification of novel CHD7 and CHD8 interacting partners will provide further insights into the pathogenesis of CHARGE syndrome and ASD/NDD." (PMID 23285124, 2012). "However, patients with KS or normosmic HH without suggestive features may also carry CHD7 mutations, and even have children with CHARGE syndrome." (PMID 21682876, 2011). "In addition, some KS patients without CHD7 mutations display CHARGE-syndrome associated phenotypic features (e.g. ear or eye anomalies), possibly implying that, in addition to CHD7, there may be other genes associated with phenotypes ranging from KS to CHARGE." (PMID 21682876, 2011). "This case shows the importance of genetic testing to confirm diagnoses, as the patient was referred to a nephrologist with a clinical diagnosis of CHARGE syndrome; however, genetic analysis of the CHD7 gene was negative." (PMID 39969027, 2025). "This situation was well documented for CHD7 gene in patients with IHH and CHARGE syndrome." (PMID 39010903, 2024). "One case was CHARGE syndrome, which was originally screened as AVSD with prenatal fetal echocardiography, diagnosed with MRI, confirmed by autopsy, and studied with GWS, which identified a c.6482del at gene CHD7 that produced a mutant peptide." (PMID 38115160, 2023). "By investigating the roles of CHD7 and PHOX2B in CHARGE, we have furthered our understanding of disease pathogenesis, with the overall goal of making anesthesia a safer process in individuals with CHARGE syndrome." (PMID 37239446, 2023). "Besides this, CHD7 and SOX2 share similar functions in the development of ectodermal lineages that are influenced in CHARGE syndrome." (PMID 34616726, 2021). "CHD7 (chromodomain helicase DNA binding protein 7) gene testing for CHARGE syndrome (OMIM #214800) was negative." (PMID 34092239, 2021). "In CHARGE syndrome patients, protein interactions are spoiled in alternative splicing of FGF8 mRNA pre-mRNA processing in neural development due to dysfunction among BRG1, SWI/SNF and CHD7." (PMID 32071290, 2020). "Several neural crest regulatory molecules are known to cause ear/kidney syndromes with variable expression of both ear and kidney phenotypes (e.g., EYA1, SIX1, SIX5, CHD7, MASP1, TBX1), involved in BOR/BO syndrome, CHARGE syndrome, 3MC syndrome and DiGeorge syndrome." (PMID 32585897, 2020). "Most of the previous studies dealing with the auditory outcome after CI or auditory brainstem implantation in CHARGE syndrome rely on clinical diagnosis only and did not perform genetic analysis of the CHD7 gene." (PMID 21931733, 2011). "No mutation was found in one patient diagnosed of typical CHARGE syndrome by direct sequencing of the 5′ UTR and coding region of the CHD7 gene." (PMID 21931733, 2011). "Although there have been many reports concerning otologic manifestations and auditory rehabilitation in CHARGE syndrome, molecular analysis of the CHD7 gene was not performed in most of the reports." (PMID 21931733, 2011). "Genetic analysis of the CHD7 gene should be performed in cases with semicircular canal aplasia even when other typical features of CHARGE syndrome are absent." (PMID 21931733, 2011). "The chd7 mutant zebrafish model effectively mimics the cardiovascular phenotype observed in CHARGE and non-syndromic patients with CHD, with the mutant zebrafish displaying abnormal first-branch arch branches similar to the clinical symptoms of patients with CHARGE syndrome." (PMID 38892128, 2024). "Mice lacking Chd7 display CHARGE syndrome-like phenotypes and exhibit abnormal expression of Ntn1." (PMID 31162046, 2019).
CHARGE syndrome (continued). "However, the contribution of Chd7 during later cerebellar development and its implication in CHARGE syndrome has not been studied, however." (PMID 28317875, 2017). "None of our three probands with CHARGE syndrome-like features carried mutations in CHD7, analyzed both by direct sequencing and MLPA, expanding the phenotypic overlap between KS and CHARGE also in patients without CHD7 mutations." (PMID 21682876, 2011). "Herein, we report a patient with a unique presentation of CHARGE syndrome, including primary hypoparathyroidism, bilateral multicystic dysplastic kidneys (MCDK), and an atypical limb anomaly; he carried a CHD7 mutation that has not been previously characterized." (PMID 21995344, 2011). "Although ES cells are not likely to be affected in CHARGE syndrome, we propose that enhancer-mediated gene dysregulation contributes to disease pathogenesis and that the critical CHD7 target genes may be subject to positive or negative regulation." (PMID 20657823, 2010). "A similar scenario with a different outcome involves subject Clin6 who was referred for EpiSign analysis as a result of negative molecular sequencing (CHD7 and SEMA3E), negative microarray, and negative exome analysis with the phenotype strongly suggestive of CHARGE syndrome." (PMID 33547396, 2021).
coloboma (41 papers, 2010 to 2025). An abnormality in which a part of a structure in one or both eyes is missing. "This study did identify a correlation between ocular abnormalities and the type of pathogenic variants in CHD7, suggesting that earlier truncating pathogenic variants resulted in more severe findings such as extensive colobomas." (PMID 36172288, 2022). "Of the 38 known coloboma‐associated genes, the analysis identified novel variants in two genes, CHD7, TFAP2A, and previously reported variants in RARB and BMP7, in a total of four unrelated families." (PMID 31816153, 2020). "Major standards include pathogenic variants in the CHD7 gene, coloboma, choanal atresia or cleft palate and ear (external, middle or inner) abnormalities." (PMID 31146700, 2019). "The major criteria of Hale proposed in 2016 were coloboma, choanal atresia or cleft palate, ear abnormalities and pathogenic CHD7 variants." (PMID 31146700, 2019). "CHD7 pathogenic variants are known to be associated with CHARGE (Coloboma, Heart, Choanal Atresia, Retardation and Ear Anomalies) syndrome (OMIM 214800)." (PMID 29293505, 2018). "A previous report also suggested functional interactions between these genes, as CHH patients with mutations in FGFR1 and CHD7 exhibit overlaps in associated phenotypes (cleft lip/palate, coloboma or ear anomalies)." (PMID 29419413, 2018). "Mutations in the gene encoding the ATP dependent chromatin‐remodeling factor, CHD7 are the major cause of CHARGE (Coloboma, Heart defects, Atresia of the choanae, Retarded growth and development, Genital‐urinary anomalies, and Ear defects) syndrome." (PMID 29168327, 2017). "RPE specific deletion of β-catenin disrupts proper RPE differentiation, resulting in the coloboma phenotype, while mutations in Chd7 and Pitx2, which are expressed in mesenchymal cells and essential for their development, cause coloboma formation." (PMID 23240058, 2012). "In comparison to the clinical features seen in CHD7 mutation positive cohort in previous studies, the incidence of choanal atresia (13%) and coloboma (38%) were relatively lower in this report, which may be a finding more specific to the Korean population." (PMID 21931733, 2011). "CHARGE syndrome (Coloboma of the eye, Heart defects, nasal choanae, growth Retardation, and Genital and urinary tract abnormalities and Ear anomalies with deafness) affects one in 10,000 births, and results from a pathogenic variant in CHD7 in two-thirds of cases." (PMID 37468646, 2024). "A few years later, xenopus was also used to demonstrate that sema3a knockdown phenocopied, although less severely, CHD7 silencing, leading to severe malformations of the craniofacial cartilage, coloboma of the eyes as well as heart defects." (PMID 33869187, 2021). "We identified novel variants in genes such as TFAP2A and CHD7, and previously reported variants in RARB and BMP7, indicating that mutations in known coloboma‐associated genes account for only 4.5% of the coloboma cohort analyzed." (PMID 31816153, 2020). "Other zebrafish models of coloboma, such as knockdown of chd7 and gdf6, in fact, result in reduced cell proliferation in the developing eye." (PMID 25004007, 2014). "Chromodomain-helicase-DNA-binding protein 7 (CHD7) plays a role in chromatin organization and is mutated in a number of human diseases including CHARGE (coloboma of the eye, heart defects, atresia of the choanae, retardation of growth/development, genital abnormalities, and ear anomalies) syndrome." (PMID 33563331, 2021). "We previously reported evidence for reduced Fgf8 expression and FGF signaling in the mid-hindbrain region of embryos heterozygous for Chd7, the gene mutated in CHARGE (Coloboma, Heart defects, choanal Atresia, Retarded growth and development, Genitourinary anomalies and Ear defects) syndrome." (PMID 29046629, 2017).
coloboma (continued). "Interestingly, in retrospect, their IHH patients with CHD7 mutations had some CHARGE features, including colobomas, deafness, ear anomalies, cleft palate and short stature; however, not to the degree that would fulfill traditional criteria." (PMID 21995344, 2011). "Results of knockdown and knockout studies contain general descriptions of microphthalmia, coloboma, and anterior defects, but an in-depth understanding of mechanism or contribution of CHD7 to these defects is lacking." (PMID 36172288, 2022). "The unexpected findings of coloboma and absence of semicircular canals led to the suspicion of CS, later confirmed by the molecular analysis of CHD7." (PMID 35987847, 2022). "In addition, this work established and qualitatively described the presence of coloboma in the Chd7 mutant mouse model which previously had not been addressed." (PMID 36172288, 2022).
Kallmann syndrome (26 papers, 2009 to 2025). Kallmann syndrome (KS) is a developmental genetic disorder characterized by the association of congenital hypogonadotropic hypogonadism (CHH) due to gonadotropin-releasing hormone (GnRH) deficiency, and anosmia or hyposmia (with hypoplasia or aplasia of the olfactory bulbs). "We identified a patient with Kallmann syndrome with a heterozygous missense variant in the CHD7 gene (NM_017780.4: c.4354G>T, p.Val1452Leu) that was originally classified as a VUS." (PMID 39596130, 2024). "Previously, we reported a Kallmann syndrome patient harboring a CHD7 missense variant classified as a VUS due to insufficient evidence of pathogenicity." (PMID 39596130, 2024). "In conclusion, our study of a patient with Kallmann syndrome uncovered an unusual missense mutation in the CHD7 gene that partially disrupts normal RNA splicing." (PMID 39596130, 2024). "Variants of chromodomain helicase DNA binding protein 7 (CHD7) gene are commonly associated with Kallmann syndrome (KS) and account for 5–6% of idiopathic hypogonadotropic hypogonadism (IHH) cases." (PMID 34563184, 2021). "In Kallmann syndrome patients with CHD7 mutations, the common brain phenotype is hypoplasia of olfactory bulb and reduced number of GnRH (gonadotropin-releasing hormone) neurons in the hypothalamus." (PMID 29033785, 2017). "CHD7 mutations are found in 5 to 10% of subjects initially classified as Kallmann's syndrome and normosmic IHH patients." (PMID 22229029, 2012). "CHD7 variants can also cause Kallmann syndrome and isolated hypogonadotropic hypogonadism." (PMID 37668839, 2023). "In addition, pathogenic variants in CHD7 have been reported in clinical cases of Kallmann syndrome, which is a disorder involving hypogonadotropic hypogonadism (deficit in gonadotropin-releasing hormone) and hyposmia or anosmia (diminished or lack of smell)." (PMID 36172288, 2022). "Besides this, CHD7 is also closely associated with Kallmann syndrome, which is a genetic heterogeneous congenital disease mainly characterized by idiopathic hypogonadotrophic hypogonadism (IHH)." (PMID 34616726, 2021). "Moreover, mutations of CHD7 have also been identified in about 6% of Kallmann syndrome (OMIM #308700), a developmental disease characterized with IHH (idiopathic hypogonadotropic hypogonadism) and anosmia." (PMID 29033785, 2017). "Furthermore, CHD7 has been found to be mutated in idiopathic hypogonadotropic hypogonadism and Kallmann syndrome." (PMID 20925924, 2010). "Interestingly, 70% of variants found in CHD7 causing Kallmann syndrome are missense variants." (PMID 36172288, 2022). "The pathogenic mechanism of Kallmann syndrome is complicated and could be partially explained by several mutated genes, including the missence mutation of CHD7, leading to the alteration of the domain or function of CHD7 protein." (PMID 34616726, 2021). "The aim of this study was to analyze the functional consequences of a heterozygous missense VUS in the CHD7 gene (c.4354G>T, p.Val1452Leu), in a patient with Kallmann syndrome with reversal of hypogonadism." (PMID 39596130, 2024). "Two nodes representing associated genes were connected to more than one node representing syndromes: the CHD7 gene, associated with both CHARGE and Kallman syndrome, and the WT1 gene, associated with Denys–Drash and Frasier syndrome." (PMID 35218153, 2022). "In Kallmann syndrome, anosmia/hyposmia is part of the clinical picture, and ANOS1, CHD7, FGFR1, PROK2, PROKR2, and SEMA3A variants were reported to be involved in isolated congenital anosmia." (PMID 32222824, 2021). "We also ruled out oligogenism by sequencing the main genes associated with nCHH and Kallmann Syndrome, although WDR11, CHD7 and SEMA3A, other genes known to be associated with CHH, have not been analyzed." (PMID 23936060, 2013). "Recently, CHD7 heterozygous mutations have been identified in subjects with hypogonadotropic hypogonadism, with and without anosmia." (PMID 22229029, 2012).
Kallmann syndrome (continued). "In addition, mutations in the CHD7 gene lead to CHARGE syndrome (coloboma, heart defects, choanal atresia, retarded growth and development, genital abnormalities, and ear anomalies) in many patients accompanying Kallmann syndrome." (PMID 32722328, 2020). "It was molecularly proven in 25 (8 CHD7 mutations, 6 FGFR1 mutations, 7 ANOS1 mutations, 2 PROKR2 mutations, 1 digenic SOX10/SEMA3F mutation, and 1 digenic ROBO3/IGFS10 mutation with anosmia and later absent puberty)." (PMID 40193582, 2025). "CHARGE and Kallmann syndromes (KS, KAL5, MIM 612370), though distinct developmental disorders, were noted to share features of impaired olfaction and hypogonadism; thus CHD7 was hypothesized to be involved in the pathogenesis of KS even in the absence of the CHARGE phenotype." (PMID 21995344, 2011).
hypogonadotropic hypogonadism (22 papers, 2012 to 2024). Abnormal ovarian or testicular function due to insufficient hormonal stimulation from the hypothalamic-pituitary axis. "Other rare and novel pathogenic variants in ANOS1, WDR11, FGFR1, RNF216, and CHD7 genes were also found in patients with Congenital Hypogonadotropic Hypogonadism." (PMID 38637882, 2024). "Heterozygous variants were detected in PROK2, WDR11 and CHD7 associated with hypogonadotropic hypogonadism, but these variants are insufficient to contribute to the POI phenotype." (PMID 37988663, 2023). "In this study, CHD7 was predicted as the target of miR-21-5p, mutations of this gene cause gonadal endocrine abnormalities, which manifests biochemically as hypogonadotropic hypogonadism (low sex steroid hormone and gonadotropin levels)." (PMID 35036174, 2021). "Novel variants in two genes linked to hypogonadotropic hypogonadism: CHD7 (c.1338A>G, p.G446G) and WDR (c.527-9T>C, intronic) were identified in the next two patients." (PMID 32612575, 2020). "Although we identified rare or novel missense variants in several hypogonadotropic hypogonadism genes (e.g. FGF17, HS6ST1, KISS1R, CHD7, IL17RD) definitively linking them to the PSIS phenotype is premature." (PMID 38096238, 2023). "Additionally, genetic causes of isolated hypogonadotropic hypogonadism such as KAL1, FGFR1/FGF8, PROKR2/PROK2, CHD7, or GNRH1 gene mutations have not been studied because the patient had a normal puberty and regular menstruation before the amenorrhea." (PMID 26266058, 2015).
choanal atresia (16 papers, 2011 to 2025). Choanal atresia (CA) is a congenital anomaly of the posterior nasal airway characterized by the obstruction of one (unilateral) or both (bilateral) choanal aperture(s), with clinical manifestations ranging from acute respiratory distress to chronic nasal obstruction. "Additional CHARGE features were present in two analyzed KS patients with P/LP variants in CHD7: proband 13 (choanal atresia), and proband 21 (ear anomaly)." (PMID 34198905, 2021). "Interestingly, the patient also has an asymmetric face and choanal atresia and a novel de novo variant of the CHD7 gene." (PMID 37521304, 2023). "While a de novo variant in CHD7, NM_032682.6:c.122T>C, p.(Met41Thr) could explain the right choanal atresia, flat angiomas and the movement disorder are likely to represent new features of this condition that had not previously been characterized." (PMID 37521304, 2023). "Developmental defects of GnRH neurons and the olfactory bulb are associated with hyposmia, rarely associated with the clinical phenotypes of synkinesia, cleft palate, ear anomalies, or choanal atresia, and may be due to mutations of KAL1, FGFR1/FGF8, PROKR2/PROK2, or CHD7." (PMID 22229029, 2012). "Previously, the presence of choanal atresia led to the first phenotypic diagnosis of CHARGE, which should have been confirmed by sequencing of the CHD7 gene." (PMID 39969027, 2025).
hearing loss (15 papers, 2013 to 2025). "We discuss the expanding phenotypic variability observed in CHD7-related disorders, highlighting the importance of considering CHD7 in nonsyndromic hearing loss cases, especially when accompanied by inner ear malformations on MRI." (PMID 38790272, 2024). "It is important to consider, however, the potential of certain gene mutations such as CDH23 or CHD7 – typically linked with syndromic forms of hearing loss – to directly affect central auditory pathways." (PMID 37697742, 2023). "Analysis of Disease Ontology terms for all differentially expressed genes showed enrichment of Chd7-associated syndromes as well as hearing loss." (PMID 34732824, 2021). "CHARGE is a syndromic hearing impairment that is predominantly caused by mutations in the chromodomain helicase DNA binding protein 7 (CHD7) gene." (PMID 24840056, 2014). "Potential causative variants were identified in genes associated with nonsyndromic hearing loss (CIB2, COL11A1, ILDR1, MYO15A, TMPRSS3, and WFS1), nonsyndromic hearing loss or Usher syndrome (CDH23, MYO7A, PCDH15, and USH2A), and other syndromic forms of hearing loss (CHD7, OPA1, and SPTLC1)." (PMID 34837038, 2022). "In a clinical sense, recognizing those IHH genes and associated phenotypes may improve our diagnostic capabilities by enabling us to prioritize the screening of particular gene(s) such as synkinesia (ANOS1), dental agenesis (FGF8/FGFR1) and hearing loss (CHD7)." (PMID 29280744, 2017). "Only recently, CHD7 variant alleles have also been implicated in the etiology of enlarged vestibular aqueduct [EVA] and associated sensorineural hearing loss." (PMID 38790272, 2024). "Causal P and LP variants were identified in 5 out of 13 patients with a history of cryptorchidism (three in FGFR1, one in ARHGAP5, and one in GNRH1), in 2 out of 8 patients with hearing impairment (CHD7 and FGFR1 genes), and in 2 out of 2 patients with renal agenesis (ANOS1 gene)." (PMID 39308770, 2024).